ZEB2-AS1 (ZEB2 antisense RNA 1)
Synonyms: ZEB2NAT; ZEB2-AS; ZEB2AS
Gene: Long non-coding RNA gene on chromosome 2 (144,517,978 to 144,521,477, forward strand). Ensembl gene ENSG00000238057.
Gene Ontology:
Biological process: positive regulation of gene expression
Diseases named in the same sentence as ZEB2-AS1 in open-access papers:
ZEB2-AS1 is named in the same sentence as 5 diseases in open-access papers, as found by Europe PMC text mining. Sharing a sentence is not in itself a finding about the gene and the disease. The quoted sentences say what the papers report.
bladder cancer (3 papers, 2015 to 2020). "Recent evidence shows that lncRNA ZEB2-AS1 (also known as ZEB2AS, ZEB2-AS, ZEB2NAT) modulates the invasion and EMT progression in bladder cancer as well as in gastric cancer." (PMID 31575017, 2019).
tumor (2 papers, 2017 to 2019). "LncRNA ZEB2AS1 can promote EMT by regulating the variable shear, which promotes tumor metastasis." (PMID 28212533, 2017).
ZEB2-AS1 also shares sentences with these, for which no sentence is quoted: cancer (1 paper); gastric cancer (1); melanoma (1).